NUAK2 (NUAK family kinase 2)
Diseases named in the same sentence as NUAK2 in open-access papers (continued):
Sharing a sentence is not in itself a finding about the gene and the disease.
tumor (continued). "Additionally, we describe two main AMPK-related kinases, Novel (nua) kinase family 1 (NUAK1) and 2 (NUAK2), which have been understudied, but play a major role in cellular physiology and tumor development." (PMID 34685740, 2021). "Additionally, NUAK1 and NUAK2 overexpression has been found in various tumor types and their upregulation is often correlated with an increased migration and invasion capacity." (PMID 34685740, 2021). "The role of NUAK1 and NUAK2 in cancer has been observed across various tumor types." (PMID 34685740, 2021). "Pathologically, the NUAK2 activation of YAP/TAZ promoted tumor growth and liver overgrowth." (PMID 34282782, 2021). "Overall, evidence suggests that NUAK1 and NUAK2 play an important role in tumor development as protein kinases and could be appealing therapeutic targets." (PMID 34685740, 2021). "For instance, NUAK2 has been shown as a tumor promoter in different tumor models." (PMID 31798532, 2019). "Importantly, we show that pharmacological inhibition or loss of NUAK2 expression blocks YAP/TAZ activity and attenuates cancer cell and tumor growth in mice." (PMID 30158528, 2018). "These intricate molecular mechanisms may partly explain the dual functions of NUAK2 as an oncogene and as a tumor suppressor gene." (PMID 21911917, 2011). "NUAK2 has been speculated to have contradictory functions on tumorigenesis as a tumor suppressor or as an oncogene." (PMID 21911917, 2011). "For Nuak2 LOF (Nuak2-CR) studies, we used a CRISPR-Cas9 approach where dual guide RNAs targeting Nuak2 were co-electroporated with tumor-generating PB-IUE plasmids." (PMID 40770117, 2025). "Complementary, GOF studies where tumor-generating PB-IUE constructs were co-electroporated with Nuak2 expression plasmid, demonstrated that overexpression of Nuak2 (Nuak2-OE) conferred significantly reduced 50% survival rates compared to control mice." (PMID 40770117, 2025). "mRNA expression levels of NUAK2, CTGF, and CYR61 were significantly decreased in CA3‐treated tumor tissue vs vehicle‐treated mice in LIV31." (PMID 39300603, 2024). "However, NUAK2 is a prognostic marker for PDAC and is associated with a favourable prognosis according to The Human Protein Atlas, which proposes a potential tumour suppressor role for NUAK2 in PDAC, suggesting that enhancing NUAK2 may be a favourable strategy for PDAC." (PMID 39110005, 2024). "NUAK2 as a member of the AMPK family has several intriguing aspects both as an oncogene and as a tumor suppressor gene." (PMID 21911917, 2011).
cancer (21 papers, 2010 to 2025). A tumor composed of atypical neoplastic, often pleomorphic cells that invade other tissues. "Cell lines most sensitive to GPX4 inhibitors had significantly higher NUAK2 expression compared to resistant cell lines (p < 0.00001, Student’s t-test), supporting an association across cancer types between NUAK2 and GPX4 inhibitor sensitivity." (PMID 35523770, 2022). "NUAK2 emerges as a crucial gene involved in the pathogenesis of diverse cancer types and represents one of the target genes regulated by the Hippo pathway." (PMID 39936032, 2025). "Human NUAK2 resides at q32.1 of Chromosome 1 in a region that is frequently amplified in several cancers, including mammary, hepatic, pulmonary, uterine and ovarian cancers, along with melanoma." (PMID 38939918, 2024). "It was recently demonstrated that NUAK2 is an essential mediator of YAP-driven cell growth, and knockdown of NUAK2 induces a decrease in migration and promotes cellular senescence of cancer cells with high YAP activity." (PMID 39071701, 2024). "As a consequence, NUAK2 has profound effects on the proliferation and migration of cancer cells; and its downstream genes, including p27 and YAP, play a critical role in the regulation of cell division cycle and motility." (PMID 39071701, 2024). "On the basis of the tumorigenic role of NUAK2 in the growth and migration of several human cancer cells, current researchers have explored the NUAK2-mediated regulation of cellular physiology in the nervous system." (PMID 39071701, 2024). "NUAK1 and NUAK2 are AMPK (AMP-activated Protein Kinase) related kinases with diverse functions in cancer cells." (PMID 36295658, 2022). "We identified GPX4 inhibitor-sensitive and resistant cell lines and compared NUAK2 expression, from Cancer Cell Line Encyclopedia RNA sequencing data, in these two groups." (PMID 35523770, 2022). "To assess the clinical relevance of these observations, we examined NUAK2 alterations across human cancers from The Cancer Genome Atlas (TCGA) data." (PMID 35523770, 2022). "Understanding Nuak2 and its role in AMPK regulation and ER stress can provide insight into the role of Nuak2 in human disease such as cancer." (PMID 35485945, 2022). "NUAK2 expression correlated with sensitivity to GPX4 inhibitors across a variety of human cancer cell lines." (PMID 35523770, 2022). "Despite the limited number of studies that experimentally elucidate the role of NUAK1 and NUAK2 in cancer development, both kinases have been found amplified in different tumors." (PMID 34685740, 2021). "By evaluating several human cancer cell lines we determine that NUAK2 is selectively required for YAP-driven growth." (PMID 30446657, 2018). "Our results thus introduce a new opportunity for cancer therapeutics by delineating NUAK2 as a potential target for re-engaging the Hippo pathway." (PMID 30158528, 2018). "Similar dual roles for NUAK2 have been reported in other cancers." (PMID 40770117, 2025). "Furthermore, the pharmacological inhibition of NUAK2 has been shown to repress YAP-dependent cancer cell proliferation and excessive liver growth." (PMID 39936032, 2025). "Others, such as miR96, miR145 and miR143 link NUAK1 or NUAK2 to more general roles in cancer." (PMID 38939918, 2024). "For instance, NUAK1 has been shown to play key roles in cancer cell survival during energetic or oxidative stress, while NUAK2 is frequently amplified in a spectrum of human cancers and both participate in facilitating cell motility required for cancer cell dissemination and metastasis." (PMID 38939918, 2024). "Knockdown of NUAK2 gene in various cancer cell lines such as BC cell lines (TCCSUP, T24), colon cancer cell lines (SW480) and breast cancer cell lines (MDA-MB231 and MDA-MB468) significantly inhibited the transcriptional activity of YAP/TAZ and the proliferation ability of cancer cells." (PMID 35912245, 2022).
cancer (continued). "Our demonstration that sensitivity to GPX4 inhibitors is correlated with NUAK2 expression across numerous cancer cell types suggests that NUAK2 expression may be a potent predictor of vulnerability to GPX4 inhibition." (PMID 35523770, 2022). "Nuak2 belongs to the AMPK protein kinase family and has mainly been linked to cancer." (PMID 35485945, 2022). "Initially, NUAK1 and NUAK2 were described in brain tissue, however, further research has demonstrated their role in cell migration and polarization, as well as invasive and metastatic processes in cancer cells." (PMID 34685740, 2021). "Additionally, it will be important to identify particular cancer genotypes that would correlate with sensitivity to NUAK2 depletion." (PMID 30446657, 2018). "Additionally, pharmacological inactivation of NUAK2 suppresses YAP-dependent cancer cell proliferation and liver overgrowth." (PMID 30446657, 2018). "We next examined the requirement for NUAK2 in the proliferation of human cancer cells." (PMID 30446657, 2018). "NUAK2 also has effects on the migration of cancer cells as speculated from studies on myosin filaments and cytoskeleton organization in normal cells." (PMID 21911917, 2011). "Disruption of the normal regulation and function(s) of NUAK2 may lead to the dysregulation of proliferation and migration in cancer cells." (PMID 21911917, 2011). "Moreover, our data suggest that NUAK2 inhibition might represent a selective vulnerability of cancer cells with high YAP activity." (PMID 30446657, 2018). "Thus, our understanding of the role of NUAK2 in cancer is still quite limited." (PMID 30446657, 2018). "Although it has not been specifically investigated in the contextof cancer, there is evidence that NUAK2 may be involved incancer-associated pathways and may have pro-survival activity." (PMID 21423607, 2011). "The spectrum of actions of NUAK1 and NUAK2 may range from the control of gene expression to the regulation of the cell cycle and cell differentiation, important cellular properties that define adult tissue homeostasis and diseases, such as tissue fibrosis and cancer." (PMID 30622137, 2019). "Our studies on cultured cancer cell lines and using an orthotopic model of mammary tumorigenesis demonstrated that abrogation of NUAK2 expression or activity blocked YAP/YAZ function and attenuated proliferation in diverse cancer contexts." (PMID 30158528, 2018). "NUAK2 and NUAK1 share roughly 60% sequence identity, and have shared functions in cytoskeletal remodeling, metabolic adaption, proliferation, and EMT—key hallmarks of cancer." (PMID 40770117, 2025). "As well as being a transcriptional target for YAP/TAZ, NUAK2 was shown to inhibit LATS1 kinase activity, and acute treatment of cancer cells with the dual NUAK inhibitors, WZ4003 or HTH-02-006, increased YAP1S127 phosphorylation and blocked nuclear translocation of YAP1." (PMID 38939918, 2024). "Interestingly, the NUAK2 inhibitor, WZ4003, contributed to the anti-cancer activity of SI-12 across seven out of eight tested cell lines but possessed a moderate rescue-like effect in PANC-1 cells." (PMID 33767353, 2021). "Considering our observations suggesting that NUAK2 is critical for YAP-driven cell proliferation and its oncogenic phenotypes, the development of NUAK2 kinase inhibitors represents an attractive avenue for intervention in YAP-driven cancers." (PMID 30446657, 2018). "Whether NUAK2 is also relevant for the regulation of Akt phosphorylation is unknown, but it would be essential to address it because NUAK1 and NUAK2 are differentially expressed in normal and cancer tissues." (PMID 38135881, 2023). "In this review, we aim to unravel the role of NUAK1 and NUAK2 as members of the AMPK-related kinase family of proteins and to examine their various cellular functions, with a focus on the implications of altered expression and the potential subsequent modified activities in different cancer types." (PMID 34685740, 2021).
cancer (continued). "Together, the data suggest that modulation of NUAK2 expression does not affect NUAK1, which is consistent with previous reports in other cancers." (PMID 40770117, 2025).
infection (1 paper, 2024). The state of being infected such as from the introduction of a foreign agent such as serum, vaccine, antigenic substance or organism. "In the case of NUAK2 mRNA, there is some degree of mRNA retention in the nucleus upon infection with the wild-type virus, which is not significantly different from the infection with the Nsp1 mutant virus, as shown by the intracellular distribution of mRNAs at the single-cell level." (PMID 38768348, 2024).
neurodevelopmental disorder (1 paper, 2024). A behavioral and cognitive disorder with onset during the developmental period that involves impaired or aberrant development of intellectual, motor, or social functions. "Since NUAK2 plays a significant role in cellular homeostasis, axon arborization, and neurodevelopmental disorders, it is important to further investigated the role of NUAK2 during all steps of neural tube regeneration, including peripheral nerve regeneration after injury." (PMID 39071701, 2024).
NUAK2 also shares sentences with these, for which no sentence is quoted: mesothelioma (2 papers); skin tumors (2); actinic keratosis (1); alcoholism (1); angiosarcoma (1); basal cell carcinoma (1); Bowen’s disease (1); brain tumor (1); colorectal (1); COVID-19 (1); diabetes (1); digestive system cancer (1); extramammary Paget disease (1); Glucose intolerance (1); Hepatic steatosis (1); Hyperglycemia (1); leukemia (1); lymphoma (1); meningioma (1); myeloma (1); neural tube defect (1); Non-Alcoholic Fatty Liver Disease (1); Obesity (1); ovarian tumor (1); pancreatic cancer (1); schizophrenia (1); squamous cell carcinoma (1).